NR4A3 (nuclear receptor subfamily 4 group A member 3)
Diseases named in the same sentence as NR4A3 in open-access papers (continued):
Sharing a sentence is not in itself a finding about the gene and the disease.
lung mucoepidermoid carcinoma (1 paper, 2020). "As AcCC cell lines are not available, we utilized NCI-H292 cells, a lung mucoepidermoid carcinoma cell line (MEC) that expresses very low levels of NR4A3 and MYB, making it a suitable model to interrogate functional interactions between the NR4A3 and Myb proteins." (PMID 32867110, 2020).
malignant mesothelioma (1 paper, 2024). A malignant neoplasm of the pleura or peritoneum, arising from mesothelial cells. "We found a female predominance, except for cases harboring NR4A3 and SUFU malignant mesothelioma, and most patients were around 60 years at diagnosis, but those harboring ALK or EWSR1/FUS::ATF1 gene fusions were younger." (PMID 39059063, 2024).
mesothelioma (1 paper, 2024). A usually malignant and aggressive neoplasm of the mesothelium which is often associated with exposure to asbestos. "The UMAP projection showed that all ALK, NR4A3, and MAP3K8-rearranged EM formed distinct subgroups, with transcriptomic similarities based on the histology and the site of mesothelioma." (PMID 39059063, 2024).
migraine (1 paper, 2022). "An existing study found that NR4A3 may be one of the many DNA methylation genes involved in the pathogenesis of migraine." (PMID 35747513, 2022).
myelodysplastic syndrome (1 paper, 2020). A clonal hematopoietic disorder characterized by dysplasia and ineffective hematopoiesis in one or more of the hematopoietic cell lines. "Previous work of our group identified a long non-coding RNA in the NR4A3 locus expressed in hematopoietic stem cells from myelodysplastic syndrome patients." (PMID 33330042, 2020).
myeloproliferative neoplasm (1 paper, 2019). A clonal hematopoietic stem cell disorder, characterized by proliferation in the bone marrow of one or more of the myeloid (i.e., granulocytic, erythroid, megakaryocytic, and mast cell) lineages. "Furthermore, the deletion of NR4A1 and NR4A3 in mice is found to lead to AML13, and redujinction in the gene dosages of NR4A1 and NR4A3 in hypoallelic mice beyond a critical threshold is sufficient to cause mixed myelodysplastic/myeloproliferative neoplasms (MDS/MPN), along with AML progression." (PMID 31839811, 2019).
ovarian carcinoma (1 paper, 2014). A malignant neoplasm originating from the surface ovarian epithelium. "In the tested ovarian cancer cell lines, B76 and HOC7, treated with IT the largest increase in mRNA expression was observed for NR4A3." (PMID 24528603, 2014).
parasitosis (1 paper, 2015). "Analyzing some individual genes, we additionally observed that transcriptional changes of outliers (i.e. NR4A3 with a lfc > 2 in the dermatological disease group and a lfc < -1 in parasitosis group) were not statistically significant." (PMID 26524763, 2015).
pneumonia (1 paper, 2026). An acute, acute and chronic, or chronic inflammation focally or diffusely affecting the lung parenchyma, caused by an infection in one or both of the lungs (by bacteria, viruses, fungi, or mycoplasma.). "By examining lung-infiltrating virus-specific T cells using Nr4a3-Tocky mice during SARS-CoV-2 infection, we identified T-cell dynamics associated with severe pneumonia." (PMID 41533733, 2026). "We addressed the age-dependent effects of SARS-CoV-2 infection on pneumonia severity using Nr4a3-Tocky mice, which were categorized into aged (30–39 weeks old) and adult (15–17 weeks old) groups (G1 aged infected, G2 aged control, G3 adult infected, G4 adult control)." (PMID 41533733, 2026). "Both aged and adult SARS-CoV-2-infected Nr4a3-Tocky mice exhibited comparable levels of inflammatory cell infiltration and T-cell activation in the lungs by flow cytometric analysis, indicating a similar potential for pneumonia development." (PMID 41533733, 2026).
pulpitis (1 paper, 2025). Inflammation of the dental pulp. "For the phenotype Pulpal and apical diseases, two other loci in chromosomes 2 (near BCL11A) and 9 (near RMI1), and for the phenotype Pulpitis, three other loci in chromosomes 1 (near PDE4B), 9 (near NR4A3), and 17 (near VMP1 and TUBD1) were identified." (PMID 40701953, 2025).
salivary carcinoma (1 paper, 2024). "Nevertheless, given the limitations of this study which includes the lack of testing for NR4A3 (NOR1) or NR4A2 (NURR1) expression, a non-secretory salivary carcinoma cannot be entirely excluded in those cases without typical 1F1O1G rearrangements." (PMID 39101978, 2024).
sarcopenia (1 paper, 2025). Progressive decline in muscle mass due to aging which results in decreased functional capacity of muscles. "Consequently, fully resolving and addressing NR4A3 regulation could have far-reaching implications for global health and constitutes an important target to mitigate the adverse effects of inactivity, sarcopenia, and metabolic disease." (PMID 40609830, 2025).
schizophrenia (1 paper, 2024). A major psychotic disorder characterized by abnormalities in the perception or expression of reality. "There are also agonists or activators for products of six DEGs that are down-regulated in ASD (Lrrk2), schizophrenia (Chrm4, Prkca), schizophrenia and BP (Klf2) or schizophrenia, BP and MDD (Nr4a1 and Nr4a3)." (PMID 39502833, 2024).
skin cancer (1 paper, 2024). "Interestingly, RNAseq data in the Human Protein Atlas give support for a possible role of NR4A3 because it is particularly upregulated in human skin cancer, and it belongs to a cluster of genes associated with skin cancer and melanin biosynthesis." (PMID 38571883, 2024).
thymic lymphoma (1 paper, 2013). "Conditional deletion of Fbxw7 in CD4+ cells, or deletion of Nr4a3 and the closely related Nr4a1, resulted in hyper-proliferation of T cells, thymic lymphoma's and lethal lymphoproliferation, a phenotype similar to Foxp3−/− mice." (PMID 23825948, 2013).
Tinnitus (1 paper, 2023). Tinnitus is an auditory perception that can be described as the experience of sound, in the ear or in the head, in the absence of external acoustic stimulation. "Meanwhile, down-regulated genes between the tinnitus and the control group were Car3, Egr2, Bcl6b, C1qtnf12, Cartpt, LOC108348062, Nr4a3, Gprc5a, LOC103690128, and Angptl6." (PMID 37190538, 2023). "The expressions of Fos (p < 0.05), Nr4a1 (p < 0.01), Nr4a3 (p < 0.05), Egr2 (p < 0.01), and Egr3 (p < 0.05) were significantly decreased in the tinnitus group compared to the non-tinnitus group." (PMID 37190538, 2023).
triple-negative breast carcinoma (1 paper, 2025). An invasive breast carcinoma which is negative for expression of estrogen receptor (ER), progesterone receptor (PR), and human epidermal growth factor receptor 2 (HER2). "Therapeutically, breast AciCCs are managed according to triple-negative breast cancer protocols, while salivary gland AciCCs may benefit from emerging targeted approaches based on NR4A3-driven oncogenesis." (PMID 41301002, 2025).
uveal melanoma (1 paper, 2023). A melanoma derived from melanocytes of the uveal tract. "Conversely, uveal melanoma cells were more sensitive to the knockdown of NR4A3 or KEAP1, mirroring the results of our screens." (PMID 37400441, 2023).
viral infection (1 paper, 2014). "We exploited virus infection techniques to induce expression of NR4A3 or three deletion mutants, and determined expression of insulin and insulin regulatory genes in MIN6 cells." (PMID 24638142, 2014). "In order to explore whether NR4A3 has an effect on insulin expression in pancreatic beta cells, viral infection was used to produce stable or transient expression of NR4A3 in the MIN6 cell line." (PMID 24638142, 2014).
ZIKV infection (1 paper, 2021). "Nr4a3 is downregulated after ZIKV infection of mice fetal neurons as identified in our microarrays, a feature that was confirmed at the RNA and the protein levels." (PMID 34048439, 2021). "Our integrative analysis and validation indicate that Nr4a3 is downregulated by miR-7013-5p, which is upregulated during ZIKV infection of neurons." (PMID 34048439, 2021). "Moreover, Npas4 and Nr4a3 were also significantly downregulated at the protein level following ZIKV infection." (PMID 34048439, 2021).
tumor (80 papers, 2012 to 2026). "Given the critical role of CDKN2AIP in cell proliferation progression 23, 24, we investigated the role and underlying mechanism of CDKN2AIP in the tumor inhibitory role of NR4A3 in HCC." (PMID 39664575, 2024). "According to the group situation of IHC, protein expression of NR4A3 was closely associated with gender and tumor size." (PMID 39664575, 2024). "The molecular hallmark of this tumor, present in over 90% of cases, is the fusion of NR4A3 with EWSR1 at 22q12.2 or TAF15 at 17q12." (PMID 37484580, 2023). "Overexpression of NR4A3 significantly attenuated the increasing of subcutaneous tumour growth caused by LINC00467 overexpression." (PMID 32125766, 2020). "CAR T-cells with deficiencies in Nr4a1, Nr4a2 and Nr4a3 showed improved tumor cell death and increased effector function." (PMID 31683815, 2019). "While ~ 25% of downregulated genes were associated with reduced H3K27ac peaks, there were only few reduced NR4A3 peaks in the tumor tissues, and only 2% of the downregulated genes were associated with reduced NR4A3 peaks." (PMID 30664630, 2019). "Expression of NR4A3 is associated with tumor size in HCC, hence, we speculated that NR4A3 may be important for HCC tumor growth." (PMID 39664575, 2024). "The expression of NR4A3 was negatively associated with tumor stage in TCGA dataset." (PMID 39664575, 2024). "In contrast, in most solid tumors, both NR4A1 and NR4A2 exhibit pro-oncogenic activity, whereas, in limited studies, NR4A3 exhibits either minimal activity or acts as a tumor suppressor." (PMID 40332813, 2025). "The representative images of mice on the Day 10 indicated that overexpressed NR4A3 inhibits tumor growth." (PMID 40762284, 2025). "Nr4a3-Tocky analysis of tumor-filtrating CD8+ T cells shows accumulation of the “arrested,” rather than “persistent,” population which have a history of antigen recognition but are no longer reengaging their antigen." (PMID 41123992, 2025). "In the RM+ group under 2D conditions, tumour suppressor genes, CDKN1A and NR4A3, were upregulated and tumour-promoting genes, CA9, EFNA1, and SUSD2, were downregulated." (PMID 41381717, 2025). "This study aimed to investigate the role and regulatory mechanisms of NR4A3, a nuclear receptor involved in apoptosis and tumor suppression, in BLCA progression, particularly its impact on anoikis resistance and metastasis." (PMID 40762284, 2025). "NR4A3 functions as a tumor suppressor in BLCA by enhancing endoplasmic reticulum stress and inhibiting anoikis resistance through the EWSR1/Ezrin pathway." (PMID 40762284, 2025). "The results indicated that NR4A3 upregulated the protein expression of CDKN2AIP and inhibited the G0/G1 phase pathway activity in xenograft tumor tissues derived from NR4A3 overexpressed cells." (PMID 39664575, 2024). "NR4A3 is a nuclear receptor and transcription factor involved in various cellular, metabolic, and tumor inhibition processes." (PMID 39474111, 2024). "Four tumor-related genes (NR4A3, CD74, PPP1R3C, and ANKRD1) with high differential expression were selected, and the GeneMANIA database was used to generate a protein–protein interaction (PPI) network diagram." (PMID 39474111, 2024). "Nr4a3 is a transcription factor involved in multiple functions in vascular biology, inflammation, glycolipid metabolism and tumor immunity." (PMID 38630738, 2024). "Through gain- and loss-of-function experiments both in vitro and in vivo, we demonstrated the tumor suppressor role of NR4A3 in hepatocellular tumorigenesis." (PMID 39664575, 2024). "And the Ki67 and PCNA percentage area of tumor cells was relatively increased in NR4A3 knockout or knockdown group when compared with their control group." (PMID 39664575, 2024). "T cells exposed to TCM from Lm-infected tumours were fully functional, as evidenced by normal Nr4a3-Timer and IFN-γ expression (Fig. EV5B)." (PMID 39558103, 2024).
tumor (continued). "Meanwhile, the diminishment of tumor growth induced by NR4A3 overexpression were significantly inhibited by CDKN2AIP knockdown in MHCC-LM3 cells, which confirming the role of CDKN2AIP in NR4A3-mediated inhibition of cell proliferation." (PMID 39664575, 2024). "NR4A3 overexpression suppresses cell proliferation, clone formation, cell cycle arrest at G0/G1 phase and tumor growth in vitro and in vivo and promote DNA damage." (PMID 39664575, 2024). "PRDM1/NR4A3 dual KO CAR T-cells demonstrated better control of tumor growth than control CAR T-cells following rechallenge." (PMID 36350986, 2022). "In this study, only PRDM1/NR4A3 double knockout anti-mesothelin CAR T-cells mediated a significant reduction in tumor burden over time (P < 0.05, fig." (PMID 36350986, 2022). "In contrast, PRDM1/NR4A3 KO CAR T-cells demonstrated a significant reduction in the proportion of PD-1+TIM-3+ CD8 T-cells in both the tumor (P < 0.05) and peripheral blood as compared to AAVS1 KO CAR T-cells (P < 0.01)." (PMID 36350986, 2022). "We found that PRDM1/NR4A3 double KO significantly increased the absolute numbers of CAR T-cells in the tumor (P < 0.05) and peripheral blood (P < 0.001) compared to AAVS1 KO CAR T-cells fig." (PMID 36350986, 2022). "Bioluminescent tumor burden was also significantly decreased by a single infusion of PRDM1/NR4A3 KO PSMA CAR T-cells compared to AAVS1 KO (P < 0.05) CAR T-cells in mice bearing intraosseous tumors generated by PC3-PSMA cell engraftment." (PMID 36350986, 2022). "Nevertheless, our findings underscore the need to balance a reciprocal upregulation of NR4A3 and NFAT signaling in the setting of PRDM1 deficiency to generate effective CAR T-cell-mediated responses in a variety of tumor types." (PMID 36350986, 2022). "At days 11 and 14, CD4+ and CD8+ tumor-infiltrating lymphocytes (TILs) were analyzed for Nr4a3-Timer, PD1, Lag3, and Ifng-YFP expression." (PMID 34534438, 2021). "We injected MC38 tumor cells into the flanks of Nr4a3-Tocky Ifng-YFP mice to examine the dynamics of tumor development and T cell responses." (PMID 34534438, 2021). "MiR-665 expression was also reported to predicts poor survival and promotion of tumor metastasis by targeting NR4A3 in BC." (PMID 33245732, 2020). "The activities of NR4A3 protein are likely cell type- or tissue-specific since the gene has been described as both an oncogene and as a tumor suppressor in different tumor types." (PMID 32867110, 2020). "Correspondingly, de-novo motif analysis of enriched NR4A3 peaks in ChIP-seq data from three AciCC tumor samples revealed the same motif in all three cases." (PMID 30664630, 2019). "The pharmacological compounds DHE and ALP are sufficient to block AML tumor growth by inducing Nr4a expression and down regulating c-Myc Nr4a3 overexpression decreased SuDHL4 B cell line proliferation and xenograph growth." (PMID 31683815, 2019). "In summary, our work highlights that the type of NR4A3 fusion protein affects tumor cell phenotype and dictates the engagement of different axon guidance cues which are expected to impact on tumor clinical behavior." (PMID 31020999, 2019). "First, we used qRT-PCR to examine the RNA expression levels of miR-665 and NR4A3 in tumor tissues of BC patients." (PMID 31209222, 2019). "There is an increase in active chromatin marks and upregulation of gene expression in AciCC tumor tissues compared to normal parotid gland that is significantly correlated with the NR4A3 transcription factor binding motif." (PMID 30664630, 2019).
tumor (continued). "Regarding the NR4A3 gene locus, there were NR4A3 binding peaks at the upstream region of the NR4A3 gene locus both in the normal parotid and tumor tissues." (PMID 30664630, 2019). "Overall, our results indicate that the type of NR4A3 chimera dictates an axon guidance switch and impacts on tumor cell biology." (PMID 31020999, 2019). "Nr4a1 knock down decreased PC3 cell line proliferation, DU145 and PC3 cells were also Nr4a3 sensitive, with Nr4a3 overexpression decreasing proliferation and tumor size and Nr4a3 proliferation increasing proliferation." (PMID 31683815, 2019). "NR4A3 methylation levels in tumor tissues were significantly higher than those found in samples from adjacent normal or gastritic tissue specimens." (PMID 27528092, 2016). "NR4A3 methylation also progressively increased according to advancement in tumor stage, grade, and lymph node metastasis." (PMID 27528092, 2016). "NR4A3 re-expression in GC cell lines sensitized the cells to cisplatin, and inhibited tumor growth in vitro and in vivo, in an animal model." (PMID 27528092, 2016). "As NR4A3 methylation associated with GC patient shorter survival, we performed immunohistochemistry (IHC) to investigate NR4A3 expression in tissue microarrays of another independent cohort containing 128 GC tumor samples." (PMID 27528092, 2016). "MALL, FHL2, PHLDA, NR4A3 and CTGF are known oncogenic factors and its gene expression is negatively associated with tumor-free survival and/or proliferation." (PMID 26187749, 2015). "Beyond these findings, future studies should explore whether NR4A3 also participates in regulating chemotherapy resistance or tumor immune response, both of which are critical components of BLCA progression and treatment failure." (PMID 40762284, 2025). "Furthermore, using subcutaneous xenografts and lung metastasis mouse models, we demonstrated that NR4A3 overexpression in vivo inhibited tumor growth, reduced lung metastasis, and improved survival." (PMID 40762284, 2025). "Hence, pathological examination using tumor-specific biomarkers, such as NR4A3, is crucial for diagnosing lesions with a latent phenotype ​​​​." (PMID 41018458, 2025). "In addition, similar protein expression was observed in NR4A3-overexpressed, NR4A3-knockout and NR4A3-downregulated mouse tumor xenografts." (PMID 39664575, 2024). "In this study, our aim was to investigate the role of NR4A3 as a tumor suppressor in HCC." (PMID 39664575, 2024). "First, it was tested whether inhibition of glycolysis could recapitulate the antagonism of TCR signalling by STm-treated tumours, i.e. Nr4a3-Timer arrest (Timer Red accumulation)." (PMID 39558103, 2024). "Additionally, the expression of NR4A3 was negatively correlated with Ki67 and PCNA in NR4A3 knockout or knockdown tumor tissues collected from nude mice with tumor xenografts." (PMID 39664575, 2024). "In addition, our IHC staining results suggest a close correlation between NR4A3 protein expression and gender as well as tumor size in HCC patients." (PMID 39664575, 2024). "Moreover, the Ki67 and PCNA percentage area of tumor cells was relatively decreased in NR4A3-overexpressing group when compared with the vector control group." (PMID 39664575, 2024). "NR4A3 is one of the members of the solitary nuclear receptor superfamily with a molecular weight of approximately 68 kDa, which has been shown to generally play tumor-suppressive roles in a variety of cancers." (PMID 37905340, 2023). "NR4A3 regulates genes involved in inflammatory response, complement activation, metabolism, pro-inflammatory signaling, cell proliferation, growth, apoptosis, survival, migration, angiogenesis, and tumor immune surveillance." (PMID 36661515, 2023). "However, triple knockout of Nr4a (including Nr4a1, Nr4a2, and Nr4a3) in CAR-T cells promoted tumor regression and prolonged the survival of tumor-bearing mice." (PMID 37596653, 2023).